C20orf202 (chromosome 20 open reading frame 202)
Tractability: No criterion of Open Targets' tractability assessment is met for any kind of drug.
Gene: Protein-coding gene on chromosome 20 (1,203,454 to 1,209,076, forward strand). Ensembl gene ENSG00000215595.
Gene Ontology:
Molecular function: protein binding
Genetic constraint (gnomAD): Loss-of-function variants: 6 observed, 6.62 expected, observed/expected ratio (o/e) 0.91, 90% interval 0.49 to 1.69. That is too few expected variants to judge how well the gene tolerates losing a copy. Missense variants: 134 observed, 121.53 expected, observed/expected ratio (o/e) 1.1, 90% interval 0.96 to 1.27. Synonymous variants: 46 observed, 49.21 expected, observed/expected ratio (o/e) 0.93, 90% interval 0.74 to 1.2.
Homologues: Orthologues: chimpanzee C20H20orf202 (99% identical), macaque C10H20orf202 (94% identical), pig C20orf202 (84% identical), dog C20orf202 (83% identical), rabbit C20orf202 (82% identical), mouse Tmem74bos (74% identical), rat Tmem74bos (69% identical). Paralogues in human: FAM167A (26% identical), FAM167B (26% identical), AARD (18% identical).